SLC29A1 (solute carrier family 29 member 1 (Augustine blood group))
Diseases named in the same sentence as SLC29A1 in open-access papers:
SLC29A1 is named in the same sentence as 120 diseases in open-access papers, as found by Europe PMC text mining. Sharing a sentence is not in itself a finding about the gene and the disease. The quoted sentences say what the papers report.
pancreatic cancer (86 papers, 2006 to 2025). "A large number of studies have documented that high SLC29A1 expression is associated with a favorable prognosis for patients with pancreatic cancer undergoing gemcitabine chemotherapy." (PMID 33783998, 2021). "did not observe an association between the expression level of SLC29A1 and the prognosis of patients with pancreatic cancer treated with neoadjuvant gemcitabine chemotherapy, potentially due to the limitation that the SLC29A1 evaluation occurred after neoadjuvant chemoradiation." (PMID 33783998, 2021). "For instance, research in pancreatic cancer demonstrates that the coadministration of HDAC inhibitors and gemcitabine enhances SLC29A1 and DCK gene expression, which are integral to gemcitabine transport and activation." (PMID 40723396, 2025). "As an example, SLC29A1 and DCK silencing via DNA methylation in some gemcitabine-resistant pancreatic cancer patients could be targeted with a pharmaco-epigenetic approach using DNMT inhibitors alongside gemcitabine." (PMID 40723396, 2025).
leukemia (22 papers, 2008 to 2026). A malignant (clonal) hematologic disorder, involving hematopoietic stem cells and characterized by the presence of primitive or atypical myeloid or lymphoid cells in the bone marrow and the blood. "Reduced AZA intracellular concentration in primary bone marrow blasts and other leukemia cell lines by SLC29A1 inhibition led to reduced cytotoxicity and DNA methylation." (PMID 36834962, 2023). "On the other hand, knockdown of SLC29A1 reduced sensitivity of leukemia and lung cancer to drugs since it plays a role in cellular uptake." (PMID 28105922, 2016). "To detect the transcription of DCK, CDA and SLC29A1, we examined mRNA expression of these genes in the leukemia blasts from the bone marrow of AML patients." (PMID 25398670, 2014). "Similarly, high expression of SLC29A1 was observed in primary leukemia blast and other human leukemia cell lines." (PMID 36834962, 2023). "The current study demonstrated that SLC29A1 mediates AZA uptake in leukemia cell lines and, importantly, provided mechanistic data linking AZA resistance with lower intracellular concentration of AZA, which is predominantly mediated by reduced expression of SLC29A1 in resistant cells." (PMID 36834962, 2023). "Collectively, these findings suggested that endogenous high expression of SLC29A1 plays a critical role in AZA uptake in primary AML blasts and leukemia cell lines." (PMID 36834962, 2023). "This was supported by increased AZA sensitivity of canine kidney and leukemia cell lines transfected with SLC28A1 compared to cells lines transfected with SLC29A1, SLC29A2, and SLC28A2." (PMID 36834962, 2023). "Interestingly, individuals without the enKoRV located in the intron of SLC29A1 gene, which has the highest enKoRV AAF in the koala population, showed 4.9-fold higher chances of developing leukemia than individuals carrying this enKoRV." (PMID 41513643, 2026).
lung carcinoma (10 papers, 2006 to 2025). "In the present study, an association of SLC29A1 rs9394992 C>T between lung cancer patients and healthy subjects after adjusting for the odds ratio showed a trend toward a protective effect against lung cancer risk (p = 0.036)." (PMID 39564037, 2024). "A trend toward a protective effect against lung cancer was observed with SLC29A1 +913C>T (9394992)." (PMID 39564037, 2024). "In line with this, both SLC29A1 and SLC29A2 are more highly expressed in human lung adenocarcinoma relative to adjacent lungs, suggesting a role in human lung cancer." (PMID 38876105, 2024). "The MAF of the SNPs, DCK -360C>G (80143932), SLC29A1 -201A>G (760370), SLC29A1 +913C>T (9394992), SLC29A3 +4967C>A (10999776) in lung cancer patients was 2%, 15%, 23.2%, and 24.4% respectively." (PMID 39564037, 2024).
Obesity (8 papers, 2019 to 2024). Accumulation of substantial excess body fat. "A missense mutation in SLC29A1 (c.647T>C, p.Ile216Thr) is associated with decreased BMI and a reduced likelihood of obesity, further underlining the role of ENT1 in human metabolism and energy homeostasis." (PMID 35790189, 2022).
biliary tract cancer (7 papers, 2013 to 2025). "Increased SLC29A1 mRNA level was suggested as a critical factor of pancreatic and biliary tract cancer cells sensitivity to chemotherapy." (PMID 28105922, 2016).
pancreatic adenocarcinoma (7 papers, 2010 to 2024). "The main transporter shown to mediate gemcitabine uptake in human cell lines is hENT1 (SLC29A1), and clinical correlation studies have shown that low expression of hENT1 in pancreatic adenocarcinoma is linked with poor outcomes of gemcitabine treatment." (PMID 39000123, 2024).
Anxiety (5 papers, 2017 to 2022). Intense feelings of nervousness, tension, or panic often arise in response to interpersonal stresses. "Initial studies on a Slc29a1-null mouse revealed that these ENT1-deficient animals displayed reduced anxiety in behavioural studies, as well as a reduced response to ethanol in spite of enhanced ethanol drinking preference." (PMID 30408123, 2018). "Other evidence was described in Slc29a1-null mice studies where authors revealed an important role of ENT1 in anxiety-related behavior in ethanol preference and consumption as well as in cardioprotection during ischemia." (PMID 28481238, 2017).
breast carcinoma (5 papers, 2016 to 2022). "Significant up-regulation of SLC29A1 in colorectal, astroglial, and breast cancer cells contributed to cisplatin resistance and increased cell viability." (PMID 28105922, 2016).
colorectal cancer (5 papers, 2016 to 2025). A primary or metastatic malignant neoplasm that affects the colon or rectum. "Results of a recent small scale functional study suggested that high SLC29A1 mRNA levels in colorectal cancer tumor tissue correlate with poor clinical response to 5-FU." (PMID 27733154, 2016). "SLC29A1 (ENT1) has been implicated in the uptake of antimetabolites, and although high expression of SLC29A1 has not been reported in oral cancer, its expression level could be associated with response to 5-FU, specifically in colorectal cancer." (PMID 40362545, 2025). "Interestingly, SLC29A1 was recently suggested as potential co-determinant of clinical response to 5-FU and its upregulation demonstrated by the present study further underpins the potential for targeted therapy of colorectal cancer." (PMID 27733154, 2016). "The expression of uc003owz/NM_001078177 SLC29A1 transcript was not significantly changed in more than 50% cases of all tumors studied, but was up-regulated in 77.5% (31 of 40, p < 0.05) colorectal cancer samples." (PMID 28105922, 2016).
ischemia (5 papers, 2012 to 2025). A hypoperfusion of the BLOOD through an organ or tissue caused by a PATHOLOGIC CONSTRICTION or obstruction of its BLOOD VESSELS, or an absence of BLOOD CIRCULATION. "Previous studies showed that tissues isolated from Slc29a1-null mice are relatively resistant to injury caused by vascular ischemia-reperfusion." (PMID 30408123, 2018).
colon cancer (4 papers, 2006 to 2024).
diffuse idiopathic skeletal hyperostosis (4 papers, 2014 to 2024). This syndrome is characterized by the association of ankylosing vertebral hyperostosis with hyperkeratosis of the soles and palms. "The loss of function in the adenosine transporter known as “equilibrative nucleoside transporter 1” (ENT1, also called SLC29A1) is associated with “diffuse idiopathic skeletal hyperostosis” in humans, which is characterized by ectopic calcification." (PMID 38392329, 2024).
neutropenia (4 papers, 2022 to 2025). A decrease in the number of neutrophils found in the blood. "The SLC29A1 (-162 + 228A>C) variant, also known as rs693955, has been reported to be associated with a shorter duration of neutropenia following chemotherapy." (PMID 40766322, 2025). "On the other hand, the SLC29A1 rs693955 polymorphism was correlated to a lower time to relapse and neutropenia recovery." (PMID 35456712, 2022). "Evidence from studies in ALL children indicates significant associations between SLC29A1, SLC28A2, SLC28A3 and ABCC4 variants and one or more of the hematological toxicity manifestations (neutropenia, agranulocytosis and leukopenia)." (PMID 36015138, 2022). "ABCC4, SLC19A1, SLC28A3, SLC29A1, SLCO1B1 genetic variants were associated with thiopurine-related toxicities; neutropenia, hepatotoxicity and treatment interruption, especially in Asians." (PMID 36015138, 2022). "For this reason, the presence of missense SNP in ABCG2, concomitant with other variants in renal drug transporters (SLC29A1 and ABCC4) in heterozygous, could affect the clinical drug efficacy in terms of risk of neutropenia." (PMID 39508043, 2024).
alcoholism (3 papers, 2011 to 2020). "In contrast, single nucleotide polymorphism study of human ENT-1 gene (SLC29A1) showed T647C variant would increase risk of alcohol withdrawal seizure, along with decreased extracellular adenosine level." (PMID 33390891, 2020).
colorectal tumors (2 papers, 2016). "These eight isoforms encoded by OGDH, COL6A3, ICAM1, PHPT1, PPP2R5D, SLC29A1, and TRIB3 genes were up-regulated in colorectal tumors, and this is in concordance with the bioinformatics data." (PMID 28105922, 2016). "On the basis of our gene expression data we may generalize, that colorectal tumors irrespective of the stage and localization share common downregulation of DPYD and upregulation of PPAT, UMPS, RRM2, and SLC29A1 transcripts." (PMID 27733154, 2016).
Hypertension (2 papers, 2018 to 2023). The presence of chronic increased pressure in the systemic arterial system. "Increased aorta stiffness is normally associated with hypertension and ageing, and is thus a paradoxical finding in this study where there was actually a decreased blood pressure in these relatively young (3-month) Slc29a1-null animals." (PMID 30408123, 2018). "Given SLC29A1’s role in regulating adenosine levels inside and outside the cell, adenosine reuptake inhibitors have been used to block SLC29A1 function for vasodilation, antithrombosis, hypertension, and renal disorders." (PMID 37438132, 2023).
Stroke (2 papers, 2012 to 2022). Sudden impairment of blood flow to a part of the brain due to occlusion or rupture of an artery to the brain. "For example, inhibition of the equilibrative nucleoside transporter 1 (ENT1, SLC29A1) is a potential treatment for ischemic heart disease, stroke, and cancer." (PMID 35563081, 2022).
acute leukemia (1 paper, 2016). A clonal (malignant) hematopoietic disorder with an acute onset, affecting the bone marrow and the peripheral blood. "Cytarabine is transported into cells by Human Equilibrative Nucleoside Transporter-1 (hENT1, SLC29A1), but the mechanisms that regulate hENT1 in acute leukemia have been scarcely studied." (PMID 27391351, 2016).
agranulocytosis (1 paper, 2024). "This case suggests that genetic variants in renal transporters ABCG2 (exonic non-synonymous variant, rs2231137), SLC29A1 (rs747199 and rs628031), and ABCC4 (3′UTR SNP, rs3742106 and rs11568658) may contribute to drug-induced agranulocytosis." (PMID 39508043, 2024).
anemia (1 paper, 2020). A reduction in the number of red blood cells, the amount of hemoglobin, and/or the volume of packed red blood cells. "Loss-of-function studies indicated that an Slc29a1-dependent mechanism promotes erythroblast survival and differentiation and attenuates anemia in an acute anemia mouse model." (PMID 33370779, 2020). "In aggregate, GATA factor-regulated Slc29a1 promoted cellular survival and erythroid differentiation ex vivo, and Slc29a1 promoted steady-state erythropoiesis and erythrocyte regeneration in bone marrow and spleen in an acute anemia model in vivo." (PMID 33370779, 2020). "This analysis provided in vivo genetic evidence that erythroid Slc29a1 protects against PHZ-induced acute anemia." (PMID 33370779, 2020). "Targeted ablation of murine Slc29a1 in erythroblasts attenuated erythropoiesis and erythrocyte regeneration in response to acute anemia." (PMID 33370779, 2020). "Genetic analyses with Slc29a1, which transports adenosine, revealed its function to promote erythrocyte development, and Slc29a1 attenuated anemia in a mouse model." (PMID 33370779, 2020). "By promoting erythroblast differentiation in spleen and BM in response to hemolytic anemia, erythroblast Slc29a1 mitigated anemia." (PMID 33370779, 2020). "However, PHZ-treated e-Slc29a1-/- mice developed more severe anemia relative to PHZ-treated Slc29a1f/f mice, exhibiting decreased RBCs (p < 0.05), total Hb (p < 0.001) and HCT (p < 0.05), and increased MCV and MCH (p < 0.05)." (PMID 33370779, 2020). "12-week old e-Slc29a1-/- mice and Slc29a1f/f mice were injected consecutively with PHZ, and CBC analysis confirmed the PHZ-induced anemia in Slc29a1f/f mice on day six." (PMID 33370779, 2020).
asthma (1 paper, 2023). "Asthma and AR share eight common genes (CLC, EMR4P, IL5RA, FRRS1, HRH4, SLC29A1, SIGLEC8, IL1RL1) that are presumed to describe the link for multimorbidity." (PMID 36825519, 2023).
retinoblastoma (1 paper, 2024). A malignant tumor that originates in the nuclear layer of the retina. "Furthermore, SLC29A1 is significantly less methylated in subtype 2 than in subtype 1 retinoblastomas." (PMID 38332874, 2024).
sensitization (1 paper, 2023). "Solute Carrier Family 29 Member 1 (SLC29A1) was point as a top novel gene for early allergic sensitization." (PMID 37330465, 2023).
Stillbirth (1 paper, 2024). Death of the fetus in utero after at least 22 weeks of gestation. "In GWAS analysis, SLC29A1 was discovered to be related to the number of stillbirths in sows." (PMID 39336733, 2024).
tumor (82 papers, 2007 to 2026). "Expression of SLC28A1 and SLC29A1 in PDAC tumor tissue have been best studied and are associated with gemcitabine response." (PMID 30477242, 2018). "Alternative transcript uc003owz/ NM_001078177 of SLC29A1 was characterized with tumor-specific overexpression in CRC that can be associated with drug resistance and sensitivity." (PMID 28105922, 2016). "ENT1 (SLC29A1) is highly expressed in most types of cancers, where it carries out most of the facilitative uptake by tumor cells of natural nucleosides and nucleoside-derived drugs, such as gemcitabine or cytarabine." (PMID 39143954, 2024). "The expression of some genes in PDAC tumor tissue, including SLC28A1 and SLC29A1, has been associated with gemcitabine response." (PMID 35740571, 2022). "We first observed the tumor-specific up-regulation of the uc003owz/NM_001078177 SLC29A1 transcript in CRC." (PMID 28105922, 2016). "SLC29A1 (ENT1) is the predominantly expressed nucleoside transporter across normal and tumor cells and facilitates the utilization of environmental nucleosides for nucleotide synthesis." (PMID 40519286, 2025). "Two TS-SLC genes, SLC29A1 (ENT1) and SLC8A1 (NCX1), are downregulated in tumor cells (TCS) via the EMT-induced zinc finger E box binding homology box 2 (ZEB2)/transforming growth factor (TGF)-BR/nuclear factor (NF)-kB pathway, or miR-223 in HCC, respectively." (PMID 36844876, 2023). "Transcript uc003owz is very minor isoform of SLC29A1 mRNA (CPM = 0.3 and 2.1 for normal and tumor accordingly)." (PMID 28105922, 2016). "Using RNA-sequencing data from The Cancer Genome Atlas, we observed a significantly higher expression of TYMS, TK-1, and SLC29A1 in tumor tissue (n = 371) than in adjacent nonmalignant tissue (n = 50; P < 0.05)." (PMID 32513905, 2020). "A possible explanation of these results is that SLC29A1 rs3734703 may increase SLC29A1 expression and in turn induce the uptake of Ara-C by AML cells and increase tumor cell apoptosis and clinical CR." (PMID 29141648, 2017). "Alternative transcript of SLC29A1 (NM_001078177) was up-regulated only in CRC samples, but not in the other tested tumor types." (PMID 28105922, 2016).
cancer (67 papers, 2006 to 2026). A tumor composed of atypical neoplastic, often pleomorphic cells that invade other tissues. "We found that the expression level of SLC29A1 (encoding hENT1) and SLC29A2 (encoding hENT2) in human fibroblasts was significantly lower than that in human cancer cell lines." (PMID 27137226, 2016). "Our cellular analyses showed that FTD incorporation into nuclear DNA in human cancer cell lines was effectively suppressed by an inhibitor of equilibrative nucleoside transporters or by siRNA-mediated downregulation of SLC29A1 mRNA." (PMID 27137226, 2016). "This approach may also benefit other types of cancer where the methylation of genes such as SLC29A1 and DCK is pivotal for the uptake and activation of nucleoside analogs." (PMID 40723396, 2025). "These specific metabolic flux–related genes, such as DNM2 (endocytosis), APOC1 (lipid transport), MRI1 (L-methionine salvage), MTAP (NAD salvage), and SLC29A1 (nucleoside import), indicate that the cancer progenitor cells represent hubs of metabolic trafficking activities." (PMID 38649187, 2024). "An example of this is the use of CRISPR to demethylate SLC29A1 and DCK promoter regions, increasing their expression, resulting in resistant cancer cells becoming resensitized to nucleoside analogs." (PMID 40723396, 2025). "CRISPR/Cas9 knockout screen and oligonucleotide arrays also suggested direct correlation between SLC29A1 expression and potency of AZA in human cancer cell lines." (PMID 36834962, 2023). "The expression of SLC29A1 alternative transcripts in cancer has not been previously analyzed." (PMID 28105922, 2016). "Other studies could not show correlation between SLC29A1 expression and the IC50 of AZA in AML and human cancer cell lines." (PMID 36834962, 2023).
infection (5 papers, 2012 to 2026). The state of being infected such as from the introduction of a foreign agent such as serum, vaccine, antigenic substance or organism. "In 546 East Asian patients with GT 1b infection and treatment with Peg-INF/RBV SLC29A1 (ENT1), rs6932345 was an independent predictive factor of treatment response, but only with small impact in comparison to IL28B rs12979860." (PMID 23342360, 2012).
renal disorders (1 paper, 2023). "SLC29A1, along with SLC29A2, are inhibited by nitrobenzylthioinosine (NBMPR), as well as dipryridamole, a vasodilator and blood thinner; dilazep, a vasodilator used in cardiopathy and renal disorders; and draflazine, a vasodilator." (PMID 37438132, 2023).
SLC29A1 also shares sentences with these, for which no sentence is quoted: acute myeloid leukemia (7 papers); epilepsy (6); pancreatic ductal adenocarcinoma (6); bladder cancer (5); cervical cancer (5); Huntington disease (5); Seizure (5); diabetes (4); metastatic disease (4); schizophrenia (4); Alzheimer disease (3); gastric cancer (3); gestational diabetes (3); glioblastoma (3); Hyperglycemia (3); intrahepatic cholangiocarcinoma (3); leiomyosarcoma (3); lymphoma (3); neurodegenerative disease (3); non-small cell lung carcinoma (3); acute lymphoblastic leukemia (2); ampullary cancer (2); angiosarcoma (2); bladder tumor (2); brain disorder (2); cholangiocarcinoma (2); choriocarcinoma (2); chronic myelogenous leukemia (2); COVID-19 (2); gastric tumor (2).
A further 62 diseases each share a sentence with SLC29A1 in 2 papers or fewer.